AQP5 (aquaporin 5)
Diseases named in the same sentence as AQP5 in open-access papers (continued):
Sharing a sentence is not in itself a finding about the gene and the disease.
colon carcinoma (continued). "AQP5 may be involved in the occurrence, development and metastasis of human colon cancer, and the increased expression of AQP5 in colon cancer tissues is related to tumour differentiation, tumour infiltration depth, lymph node metastasis and TNM stage." (PMID 32662230, 2020). "AQP5 expression is up‐regulated in colon cancer, but its exact role in normal and cancer cells remains unclear, and increasing studies are being performed to elucidate how AQP5 induces tumorigenesis." (PMID 32662230, 2020). "Deletion of AQP5 could increase sensitivity to chemotherapeutic drugs by the inhibition of p38 MAPK pathway in colon cancer cells." (PMID 25886458, 2015). "Patients with colon cancer expressed with AQP5 had more chances to appear liver metastasis." (PMID 25886458, 2015). "Moreover, we have previously reported the induction of AQP5 expression in its message during the early colon cancer development." (PMID 18478076, 2008). "In addition, we have reported that AQP5 triggers Ras/ERK/Rb pathway in HCT116 colon cancer cell line, thereby promoting cell proliferation." (PMID 18612408, 2008). "Besides, AQP5 and AQP9 were associated with the resistance of colon cancer to drugs." (PMID 25886458, 2015). "Additionally, we have recently reported a study which describes an induced expression of AQP5 protein during colorectal carcinogenesis and molecular pathways how AQP5 protein expression can influence colon cancer development by its interaction with the Ras/ERK/Rb signaling pathway." (PMID 18478076, 2008). "For example, AQP5 overexpression in colon cancer cells promotes cell proliferation via the Ras signaling pathway, probably mediated by the phosphorylation of the PKA consensus site of AQP5, and contributes to EMT by increasing phosphorylated Smad2/3 levels." (PMID 39941100, 2025). "In another experiment it was observed that AQP5 siRNA or a p38 MAPK antagonist inhibited p38 phosphorylation in HT-29 cells, suggesting this cascade pathway is involved in MDR colon cancer." (PMID 38336645, 2024). "They observed that AQP5 inhibits HT29 cell proliferation and regulates the molecular mechanism of colon cancer cell resistance." (PMID 32662230, 2020). "Genetic knockdown of AQP5 increased sensitivity to chemotherapy and downregulated p38 MAPK signaling in colon cancer cells." (PMID 32679804, 2020). "Among the markedly increased genes in SSA/Ps that have also been reported to be increased in colon cancer were REG4, AQP5, MUC2, TFF1, KLK10." (PMID 24533081, 2014). "AQP5 has been shown to activate EGFR and consequently to induce the MAPK signaling pathway in several types of cancer, such as glioma, lung adenocarcinoma, colon cancer, and also pancreatic cancer." (PMID 40305202, 2025). "The expression of Aquaporin 5 was positively correlated with drug resistance in colon cancer, and silencing of Aquaporin 5 suppressed p38 MAPK signaling and improved drug resistance in colon cancer cells." (PMID 29093644, 2017). "Thus, AQP5-p38 MAPK pathway and AQP9 would be a new therapeutic target to improve drug resistance of colon cancer." (PMID 25886458, 2015). "Hepatic cancer expresses similar types of AQPs with colon cancer, e.g. AQP1, AQP3, AQP5, and AQP9." (PMID 25886458, 2015). "Third, the expression of AQP5, not AQP1, or AQP3, was found to be associated with Ras/ERK/Rb pathway activation in colon cancer cell lines and was linked with liver metastasis in colon cancer patients." (PMID 18478076, 2008). "Most recently, we have demonstrated that AQP5 promotes cell proliferation and that its overexpression is related with liver metastasis; we have also found molecular pathways based on the Ras/ERK/Rb signaling pathway as a mechanism to promote cell proliferation in colon cancer cells." (PMID 18612408, 2008).
colon carcinoma (continued). "We still do not understand the link between H2O2 transport through aquaporins and the tumor malignancy, nor with the therapy resistance, but a study on colon cancer cells correlated the higher expression of AQP3 and AQP5 with the resistance to H2O2-induced stress." (PMID 37175840, 2023).
gastric cancer (22 papers, 2013 to 2025). A primary or metastatic malignant neoplasm involving the stomach. "AQP5 upregulation is also associated with lymph node metastases and lymphovascular infiltration, which are all connected with the severity of gastric carcinoma." (PMID 38336645, 2024). "On the other hand, the survival analysis demonstrated that AQP5 mRNA expression was associated with poor OS to all gastric cancer patient especially in male patients." (PMID 29678898, 2018). "AQP3 and AQP5 are upregulated in gastric carcinoma, and are associated with lymph node metastasis and lymphovascular invasion." (PMID 24918928, 2014). "Similarly, high AQP5 mRNA expression was associated with longer OS in stages I and IV gastric cancer patients." (PMID 29678898, 2018). "In vitro models using gastric cancer cell lines revealed that AQP5 inhibition reverses the pro-migratory and invasive effects mediated by Panx1, further establishing the functional connection between these molecules in gastric cancer progression." (PMID 40978734, 2025). "In gastric cancer, AQP5 serves as a surface marker of cancer stem cells (GC-CSCs), co-localizing with LGR5." (PMID 40806720, 2025). "Recent studies show that AQP5 is enriched for stem cells in gastric cancer and early gastric cardia adenocarcinoma." (PMID 40102611, 2025). "Overexpression of AQP3 and AQP5 has been reported in gastric carcinoma, where the level of expression has correlation with metastasis of lymph nodes and lymphatic vascular aggression." (PMID 40100646, 2025). "This research intends to investigate the role and the molecular mechanism of AQP5 on enriched gastric cancer stem cells (GCSCs)." (PMID 38947397, 2024). "Huang and colleagues revealed that AQP5 expression was significantly elevated in gastric cancer tissues and that suppressing AQP5 expression with acetazolamide inhibited the proliferation and invasiveness of gastric cancer cells." (PMID 38336645, 2024). "Inhibition of AQPs by HgCl2 dramatically reduced the percentage of differentiated cells and alkaline phosphatase activity in the human gastric cancer cell line MKN45 that stably expressed AQP5." (PMID 38336645, 2024). "HgCl2, an AQP inhibitor, markedly reduced the number of differentiated cells and alkaline phosphatase activity in MKN45 gastric carcinoma cells that firmly showed AQP5 activity." (PMID 38336645, 2024). "Inhibition of the expression of AQP5 in gastric carcinoma cells by acetazolamide has been described, leading to the decrease in the potential of invasion and proliferation of neoplastic cells." (PMID 36766810, 2023). "Single-cell sequencing was used to analyze the highly expressed genes in cancer stem cells of gastric cancer patients, and it was verified that AQP5 was specifically highly expressed in gastric cancer stem cells (GC-CSCs) in vivo and in vitro." (PMID 36372898, 2022). "To delineate the mutual interaction of AQP5 with classical stem cell markers, we examined gastric cancer data in TCGA." (PMID 36372898, 2022). "Then, we evaluated the pathological and clinical value of AQP5 using a gastric cancer tissue microarray." (PMID 36372898, 2022). "Next, we examined the impact of AQP5 on gastric cancer development and analyzed AQP5 mRNA and protein levels in a cohort of 30 GCs and GMs." (PMID 36372898, 2022). "AQP5 was significantly upregulated in CSCs isolated from gastric cancer patients and in spheroid cells, and AQP5 was coexpressed with the canonical stem marker LGR5." (PMID 36372898, 2022). "Our findings demonstrate that AQP5 is highly expressed in GCs and is clinically correlated with the progression of gastric cancer." (PMID 36372898, 2022). "Together, these findings suggest that AQP5 plays a critical role in the tumorigenesis of gastric cancer." (PMID 36372898, 2022). "To confirm the expression pattern of AQP5 in gastric cancer, we performed multicolor immunofluorescence." (PMID 36372898, 2022).
gastric cancer (continued). "Up-regulation of AQP5 has been suggested to play an important role in the differentiation, tumorigenesis, and progression of gastric cancer." (PMID 29678898, 2018). "Subsequently, a similar effect was detected for AQP5 protein expression in gastric cancer patients through HPA database." (PMID 29678898, 2018). "On the one hand, the upregulation of the expression of AQP3 and AQP5 in the stomach indicates their important roles in the development of gastritis and gastric cancers." (PMID 27589719, 2016). "AQP5 promotes the proliferation and migration of human gastric carcinoma cells, and its overexpression was correlated with enhanced lymph node metastasis." (PMID 27589719, 2016). "Overexpression of AQP5 enhanced whereas, inhibition of AQP5 by acetazolamide significantly attenuated the proliferation and migration of gastric carcinoma cells." (PMID 25344048, 2014). "Similarly, AQP5 is upregulated in gastric cancer stem cells and contributes to their self-renewal by modulating autophagy." (PMID 40806720, 2025). "AQP5, a marker for stemness in gastric cancer, was one of the most significantly upregulated genes." (PMID 40102611, 2025). "Aqp5 expression in cells can potentially give rise to invasive gastric cancer in mouse models." (PMID 39140283, 2024). "The group also showed that altered expression and localisation of Aqp5 could help understand the mechanism of gastric cancer initiation." (PMID 39140283, 2024). "Mechanistically, AQP5 regulated the autophagy and stemness of gastric cancer stem cells by recruiting E3 ligase Tripartite Motif Family Like 1 (TRIM21) to the key autophagy protein Unc-51 Like Autophagy Activating Kinase 1 (ULK1) and inducing the ubiquitination of ULK1." (PMID 37681902, 2023). "AQP3 and AQP5 ensure significant functions in gastric cancer." (PMID 37681902, 2023). "However, AQP5 can clearly distinguish these cell populations, suggesting that AQP5 is a more suitable target for the treatment of gastric cancer than LGR5." (PMID 36372898, 2022). "The results suggest that CSCs express their own specific marker that reflects their own tumor origin, highlighting the importance of AQP5 as a specific marker of gastric cancer that could be targeted by potential novel therapeutic strategies." (PMID 36372898, 2022). "Thus, our study identified a specific GC-CSC surface marker, AQP5, with biological, mechanistic, and clinical impacts on human gastric cancer." (PMID 36372898, 2022). "More recently, AQP5+ stem cells are identified as a source of Wnt-driven gastric cancer, and AQP5+ tumor cells could reproducibly generate organoids in the absence of exogenous growth factors, indicating the stem potential of this cell populations." (PMID 33043003, 2020). "In which, we revealed AQP3, AQP9, and AQP11 mRNA expression were associated with improved OS in all gastric cancer patients especially with intestinal subtypes, whereas AQP0, AQP1, AQP4, AQP5, AQP6/2L AQP8, and AQP10 mRNA expression were associated with poor OS in all gastric cancer patients." (PMID 29678898, 2018). "Thus, AQP5 is highly expressed and clinically correlated with the progression of gastric cancer." (PMID 36372898, 2022). "In addition, we wanted to analyze the biological functions of AQP5 in gastric cancer development." (PMID 36372898, 2022). "Furthermore, AQP5 up-regulation has additionally been noticed in human gastric cancer." (PMID 29678898, 2018). "In addition, AQP3, AQP4 and AQP5 exhibited differential expression between human gastric carcinomas and corresponding normal tissues; AQP3 and AQP5 protein expression was detected as remarkably stronger in the human carcinoma tissues than that in normal mucosa by immunofluorescence." (PMID 27589719, 2016). "Stem cells expressing AQP5 were shown to act as a source for WNT-driven, invasive gastric cancer in mouse models." (PMID 40102611, 2025).
gastric cancer (continued). "The impact of Panx1 also extends to gastric cancer, where its overexpression facilitates epithelial-mesenchymal transition (EMT) through the regulation of aquaporin 5 (AQP5), a critical mediator of signaling pathways involved in cell migration and invasion." (PMID 40978734, 2025). "Thus, we hypothesized that the AQP5 + /LGR5 + stem cell bank is the origin of gastric cancer." (PMID 36372898, 2022). "Furthermore, our study creates a link between AQP5 and LGR5 and highlights the necessity of targeting both surface markers simultaneously as a promising approach for the treatment of gastric cancer patients." (PMID 36372898, 2022). "AQP5 and LGR5 were colocalized in gastric cancer tissue cells." (PMID 36372898, 2022). "For example, the mRNAs of AQP1, AQP3, AQP4, AQP5 and AQP11 are also found in human gastric cancers." (PMID 27589719, 2016). "In addition, AQP10 and AQP5 mRNA expression with positive HER2 and AQP1 and AQP2 mRNA with negative HER2 were associated with poor survival in gastric cancer patients." (PMID 29678898, 2018). "Similarly, AQP5 protein had low expression in normal tissues, whereas AQP11 protein had higher expression in normal gastric tissues, but both proteins have medium expression in cytoplasm and membranous region of gastric cancer tissues." (PMID 29678898, 2018).
Sepsis (22 papers, 2013 to 2026). Sepsis is defined as life-threatening organ dysfunction caused by a dysregulated host response to infection. "In patients with sepsis, elevated methylation levels at the cytosine site nt-937 within the AQP5 promoter are linked to augmented AQP5 mRNA expression and are predictive of an elevated risk of mortality within 30 days." (PMID 39544938, 2024). "Here, the C allele, which is associated with decreased AQP5 expression and increased survival in severe sepsis, is associated with a decreased neutrophil cell migration in vitro." (PMID 38338680, 2024). "It is noteworthy that elevated AQP5 mRNA expression has been linked to unfavorable outcomes in sepsis patients, underscoring its potential as a prognostic marker." (PMID 39544938, 2024). "Aqp5 knockout (KO) mice exhibited significantly higher survival rates post-LPS injection compared to wild-type (WT) mice, indicating that Aqp5 deficiency exerts a protective effect in sepsis." (PMID 39544938, 2024). "Taken together, our results suggest that decreased AQP5 expression associated with decreased immune cell migration should be beneficial in sepsis." (PMID 38203778, 2024). "The initial investigation sought to ascertain the correlation between the AQP5 promoter -1364A/C polymorphism and 30-day survival in patients with severe sepsis." (PMID 39544938, 2024). "Altered expression of AQPs, such as AQP1, AQP3, and AQP5, correlates with sepsis severity, and polymorphisms in AQP5 have been linked to better survival rates and improved outcomes in sepsis-related acute respiratory distress syndrome (ARDS)." (PMID 39544938, 2024). "Substitution of cytosine for adenosine at position -1364 is associated with decreased AQP5 expression and has a significant impact on survival in patients suffering from sepsis." (PMID 39768394, 2024). "Specifically, the 1364 A/C polymorphism in the gene promoter region of AQP5 has been extensively studied in sepsis." (PMID 38203657, 2023). "The C-allele which is associated with lower gene expression in sepsis is accompanied by a higher methylation level of the AQP5 promoter." (PMID 36233114, 2022). "Accordingly, these results suggest a protective impact of a lower AQP5 expression in sepsis, and mechanisms linked to an altered AQP5 expression are of great interest." (PMID 36233114, 2022). "The quantity of aquaporin 5 protein in neutrophil granulocytes is associated with human sepsis-survival." (PMID 36233114, 2022). "Remarkably, genetic knock out or loss-of-function single-nucleotide polymorphism in the AQP5 gene promotor resulted in experimental and clinical improvement of sepsis and adult respiratory distress syndrome (ARDS) outcome." (PMID 33567720, 2021). "A promising candidate gene for investigation of sepsis-associated AKI is the water channel Aquaporin 5 (AQP5) since AQP5 is not only associated with transcellular and renal fluid transport, but also with cell proliferation and key mechanisms of inflammation." (PMID 32272738, 2020). "Our previous studies already elucidated that the AQP5 genotype is associated with outcome in sepsis and acute respiratory distress syndrome (ARDS), both suggesting a protective role of the C-allele." (PMID 32272738, 2020). "In this study, we considered an altered AQP5 expression documented to be evoked by the common AQP5 -1364A/C promoter SNP as a promising risk factor for sepsis-associated AKI." (PMID 32272738, 2020). "Altered aquaporin 5 (AQP5) expression in immune cells impacts on key mechanisms of inflammation and is associated with sepsis survival." (PMID 31811204, 2019). "Substitution of cytosine for adenosine at position -1364 is associated with decreased AQP5 expression and had significant impact on survival in patients suffering from sepsis." (PMID 30517197, 2018). "The C-allele of the aquaporin (AQP5) -1364A/C polymorphism is associated with decreased AQP5 expression but increased 30-day survival in patients with severe sepsis." (PMID 27871297, 2016).